SESN2 (sestrin 2)
Diseases named in the same sentence as SESN2 in open-access papers (continued):
Sharing a sentence is not in itself a finding about the gene and the disease.
endometrial cancer (continued). "Thus, our study implicates SESN2 to be a potential candidate in the treatment of endometrial cancer." (PMID 32899752, 2020). "Additionally, knockdown of SESN2 promoted cell proliferation, migration, and ROS production in endometrial cancer cell lines HEC-1A and Ishikawa." (PMID 32899752, 2020). "However, SESN2 mRNA and protein expression was upregulated in endometrial cancer patient tissues where mTORC1 activity was still high." (PMID 32899752, 2020). "Furthermore, we tested the protein expression of SESN2 using immunoblotting in the endometrial cancer and normal tissues." (PMID 32899752, 2020). "As SESN2 inhibits the mTOR activity, we checked whether mTORC1 inhibition in cells with depleted levels of SESN2 influences endometrial cancer cell proliferation and ROS production." (PMID 32899752, 2020). "However, mTORC1 activity was significantly higher in endometrial cancer tissues of the patients than in normal endometrial tissues, despite a significant increase in SESN2 expression." (PMID 32899752, 2020). "SESN2 was upregulated more in endometrial cancer tissues than in normal endometrial tissues." (PMID 32899752, 2020). "Furthermore, upregulation of SESN2 statistically correlated with shorter overall survival and disease-free survival in patients with endometrial cancer." (PMID 32899752, 2020). "Moreover, in a xenograft nude mice model, endometrial cancer growth increased by SESN2 knockdown." (PMID 32899752, 2020). "Moreover, overexpression of SESN2 reduced mTORC1 activation in endometrial cancer cell lines." (PMID 32899752, 2020). "Thus, the results identified SESN2 as a potential therapeutic target in endometrial cancer." (PMID 32899752, 2020). "Thus, it appears that poor prognosis in endometrial cancer patients is caused by hyperactivation of the mTORC1 pathway rather than by high SESN2 expression." (PMID 32899752, 2020). "Thus, we investigated whether expression of SESN2 correlates with that of the EMT markers, including CDH1 (encoding E-cadherin) and CDH2 (encoding N-cadherin), in the same dataset of endometrial cancer patients." (PMID 32899752, 2020). "However, the role of SESN2 in human endometrial cancer remains to be investigated." (PMID 32899752, 2020). "Subsequent experiments on endometrial cancer cell lines (HEC-1-A and Ishikawa) produced contradictory results: silencing SESN2 in these cell lines enhanced mTORC1 activity, increased proliferation, and raised intracellular ROS levels." (PMID 40361504, 2025). "The other two members of Sestrin family, SESN2 and SESN3 have been reported to be involved in anoikis resistance in endometrial cancer cell lines." (PMID 38516781, 2024). "Treatment with both agents reversed endometrial cancer cell proliferation, migration, and EMT marker expression in the SESN2 knocked-down cells." (PMID 32899752, 2020). "The results revealed a significant positive correlation between the expression of SESN2 and RPTOR in endometrial cancer patient tissues (r = 0.34, p = 4.5 × 10−6)." (PMID 32899752, 2020). "Taken together, these results suggest that SESN2 suppresses EMT and migration in endometrial cancer cells via a mTORC1-dependent mechanism." (PMID 32899752, 2020). "Moreover, SESN2 and SESN3 have been reported involved in anoikis resistance of endometrial cancer cell lines, which are regulated by miRNAs." (PMID 38516781, 2024). "It was shown that the interaction between sestrin 2 and miR-141 affected the anoikis resistance of human endometrial cancer cell lines KLE, RL-95-2, Ishikawa, and AN3CA; inhibiting miR-141 increased sestrin 2 protein expression, resulting in enhanced anoikis resistance." (PMID 34784907, 2021). "SESN2 expression is higher in endometrial cancer tissues than normal endometrial tissues, and its knockdown stimulated endometrial cancer cell proliferation and tumor growth in vivo, as observed in a mouse xenograft model." (PMID 32899752, 2020).
endometrial cancer (continued). "This suggested SESN2 to function as a negative feedback regulator of mTORC1 to inhibit endometrial cancer growth and progression stimulated by hyperactivation of mTOR signaling." (PMID 32899752, 2020). "Our data thus suggest that these correlations between SESN2 and cell cycle-associated genes are independent of the role of CDKN1A and CDKN1B as tumor suppressors in the tumor of patients with endometrial cancer." (PMID 32899752, 2020). "In endometrial cancer patient tissues, inhibition of mTORC1 activity was not effectively mediated by the negative feedback regulation of SESN2, whereas in endometrial cancer cell lines, lentiviral overexpression of SESN2 effectively suppressed mTORC1 activity." (PMID 32899752, 2020). "Next, to investigate the prognostic significance of SESN2 in endometrial cancer, we examined its expression in cancer and corresponding normal counterparts using TCGA database." (PMID 32899752, 2020). "In our study, the enforced expression of SESN2 mRNA as well as SESN2 protein was found in three endometrial cancer cell lines Ishikawa, AN3CA, and RL-95-2 but not in KLE cell line." (PMID 31073887, 2019). "Additionally, SESN2 knockdown promoted EMT and migration of endometrial cancer cells." (PMID 32899752, 2020).
lung adenocarcinoma (7 papers, 2015 to 2025). A carcinoma that arises from the lung and is characterized by the presence of malignant glandular epithelial cells. "The loss of SESN1 and SESN2 in A549 lung adenocarcinoma cells facilitates tumour growth and enhances resistance to apoptosis." (PMID 40361504, 2025). "The rapid wound closure in shSesn2-2 cell supported that deficiency of Sesn2 promotes cell migration of lung adenocarcinoma A549 cells." (PMID 25962159, 2015). "To rule out exclusiveness of the effect of Sestrins on STAT3 in A549 cells, we also silenced SESN2 in another lung adenocarcinoma cell line, H460, and observed upregulation of STAT3 phosphorylation in these cells." (PMID 39985075, 2025). "To explore the effects of Sesn2 on cell growth and cell migration, we established a Sesn2 silencing cell line by infecting retroviral shSesn2-2 into lung adenocarcinoma A549 cells." (PMID 25962159, 2015). "We have previously reported that silencing of SESN1 or SESN2 stimulates the growth of lung adenocarcinoma A549 tumor xenografts in nude mice, which is in contrast with the negative effect of SESTRINs’ inactivation on tumor growth in the KrasLSL-G12D-based mouse model." (PMID 31857853, 2019). "However, in the A549 cell line obtained from advanced lung adenocarcinoma, SESN2 did not contribute to the activation of AKT and sensitised cancer cells to cell death and pro-apoptotic cytokines." (PMID 40361504, 2025). "However, phosphorylation of AKT and S6 was not changed in the lung adenocarcinoma A549 cells with the knockout of the SESN1 and/or SESN2 genes, indicating that pro-oncogenic signaling pathways activated during carcinogenesis may overcome the need for SESTRINs to support the high activity of AKT." (PMID 31857853, 2019).
osteosarcoma (7 papers, 2018 to 2024). A usually aggressive malignant bone-forming mesenchymal neoplasm, predominantly affecting adolescents and young adults. "To further explore the underlying role of SESN2 in the drug resistance of osteosarcoma cells, we reduced SESN2 expression via lentivirus transduction with a plasmid containing shRNA targeting SESN2." (PMID 34646824, 2021). "Subsequent analysis showed that chemotherapy treatment of SESN2-knockdown osteosarcoma cells not only caused intracytoplasmic calcium accumulation and ER swelling and vacuolisation but also enhanced PERK-mediated phosphorylation of eIF2α." (PMID 34646824, 2021). "Studies should focus on determining the role of SESN2 in osteosarcoma cells with a particular focus on autophagy and its potential effects on drug resistance, and the underlying molecular mechanism of chemotherapy-driven SESN2-mediated autophagy in osteosarcoma also needs to be explored." (PMID 34646824, 2021). "The experimental silencing of SESN2 increased the sensitivity of osteosarcoma cells to chemotherapeutic agents and increased their apoptosis rate." (PMID 37284849, 2023). "Such phenomenon of SESN2 activity emerges from increased endoplasmic stress induced by chemotherapeutic agents in osteosarcoma cell lines." (PMID 37284849, 2023). "In accordance with our study, in osteosarcoma, the inhibition of chemotherapy-increased SESN2 expression prevented chemoresistance through the inhibition of autophagy and induction of apoptosis." (PMID 36611970, 2022). "In SESN2 silenced osteosarcoma cells, they observed inhibited autophagy and increased apoptosis, as well as reduced tumor progression, in a mouse model." (PMID 36611970, 2022). "TUNEL staining showed that SESN2 knockdown induced more apoptosis in osteosarcoma cells after chemotherapy treatment compared to that in control cells subjected to chemotherapy treatment." (PMID 34646824, 2021). "In summary, our data show that SESN2 expression in osteosarcoma cell lines is increased in response to chemotherapeutic agents." (PMID 34646824, 2021). "We then used flow cytometry to investigate the relationship between ER stress and apoptosis and found that 4-PBA (5 mM) reduced chemotherapy-induced apoptosis in osteosarcoma cells with SESN2 knockdown." (PMID 34646824, 2021). "The inhibition of osteosarcoma cell proliferation upon SESN2 knockdown in cells treated with chemotherapeutic drugs was measured by the CCK-8 kit and colony formation assay." (PMID 34646824, 2021). "Flow cytometry confirmed that SESN2 knockdown increased the sensitivity of osteosarcoma cells to chemotherapeutic agents and increased their apoptosis rates compared with those of the control shRNA-treated group." (PMID 34646824, 2021). "We suggest that chemotherapeutic agents induce autophagy in a SESN2-dependent manner by downregulating mTOR phosphorylation, which further promotes the inhibition of chemotherapeutic drug-induced apoptosis of osteosarcoma cells." (PMID 34646824, 2021). "These experimental results indicate that SESN2-mediated autophagy reduces the sensitivity of osteosarcoma cells to chemotherapy drugs, leading to the occurrence of drug resistance." (PMID 34646824, 2021). "To analyse the expression of SESN2 in osteosarcoma cells after chemotherapy, we detected the expression of SESN2 in HOS, MG63 and 143B cells treated with Cis (20 μmol/L), Dox (0.2 μg/mL) or Mtx (50 μmol/L)." (PMID 34646824, 2021). "In this study, we found that SESN2 expression was upregulated in osteosarcoma cells during chemotherapy; thus, we further investigated the effects of SESN2 on the proliferation, apoptosis, drug resistance of osteosarcoma cells." (PMID 34646824, 2021). "In concurrence with these findings, we provide the schematic diagram of reciprocal signal axis regulation, which is operative in TIIA-induced SESN2-dependent growth inhibition of osteosarcoma cells." (PMID 30258193, 2018).
osteosarcoma (continued). "Herein, our study reveals that TIIA treatment induces SESN2/AMPK-α upregulation in osteosarcoma cells." (PMID 30258193, 2018). "We also demonstrate that HGK-SAPK/JNK-Jun signal axis results in induction of TIIA-mediated autophagy and osteosarcoma growth inhibition, and their recruitment to SESN2 promoter leads to SESN2/AMPK-α activation." (PMID 30258193, 2018). "Based on the presented results, SESN2 protein could have such potential to be a modulator of osteosarcoma cell response to chemotherapy." (PMID 37284849, 2023). "At the same time, elevated SESN2 level could act as a predicting factor in osteosarcoma cells’ response to cisplatin, doxorubicin and methotrexate." (PMID 37284849, 2023). "Furthermore, in osteosarcoma cells, chemotherapy-induced SESN2 expression promoted autophagy, which diminished tumor cell apoptosis." (PMID 36611970, 2022). "In addition, we explored the potential mechanism by which SESN2 promotes drug resistance in osteosarcoma cells through increased autophagy." (PMID 34646824, 2021). "Therefore, our results suggest that SESN2 is a novel therapeutic target for drug resistance in osteosarcoma." (PMID 34646824, 2021). "Moreover, upregulated SESN2 expression decreased the expression of ER stress-related proteins in osteosarcoma cells treated with chemotherapy drugs." (PMID 34646824, 2021). "In addition, knockdown of SESN2 decreased autophagy and increased apoptosis, which corresponds to increased sensitivity of osteosarcoma cells to chemotherapeutic agents." (PMID 34646824, 2021). "Annexin V-PE staining revealed that the apoptosis of SESN2-overexpressing osteosarcoma cells treated with Dox (0.2 μg/mL) and 3-MA (3-methyladenine, 5 mM) was significantly higher than that in cells treated with Dox (0.2 μg/mL) alone and was close to the apoptosis of the control cells." (PMID 34646824, 2021). "However, little is known about the role of SESN2-dependent autophagy in drug resistance of human osteosarcoma." (PMID 34646824, 2021). "Our results reveal that SESN2 and p-AMPK downregulation were associated with osteosarcoma formation, and further indicated that elevation of SESN2 and p-AMPK expression by TIIA could be related to its anticancer effects." (PMID 30258193, 2018). "While the crucial role for the HGK-SESN2 axis in TIIA-mediated transcriptional induction of SESN2 in vitro has been determined, the level of SESN2 and its significance in human osteosarcoma remain unclear." (PMID 30258193, 2018). "We found an association between SESN2 and autophagy pathways and observed that SESN2 inhibited the ER stress signalling pathway PERK-eIF2α-CHOP following treatment with chemotherapy, thereby upregulating autophagy in osteosarcoma cells, which was accompanied by a slight decrease in P62." (PMID 34646824, 2021). "The HGK (MAP4K4 or mitogen activated protein kinase kinase)-SAPK/JNK-Jun signal axis can be recruited to the SESN2 promoter to activate SESN2/AMPK-α and induce Tan IIA -mediated autophagy and osteosarcoma growth inhibition." (PMID 34819867, 2021). "By utilizing human osteosarcoma clinical specimens, we show that both SESN2 and p-AMPK (Thr172) are downregulated in a majority of patients with osteosarcoma, and low p-AMPK staining was reported to be correlated with poor prognosis of several cancers." (PMID 30258193, 2018). "We supposed that TIIA treatment induces autophagy via upregulation of p-AMPK-α in a SESN2-dependent manner, which further contributes to TIIA-mediated inhibition of anchorage-independent growth of osteosarcoma cells." (PMID 30258193, 2018).
osteosarcoma (continued). "While HGKshRNA was applied to knock down endogenous HGK expression in both of the osteosarcoma cells, it not only blocked HGK activation but also attenuated p-SAPK/JNK/p-c-Jun and SESN2 induction and LC3-II formation following TIIA treatment." (PMID 30258193, 2018). "We looked for a link between SESN2 and the autophagy pathway and found that SESN2 promoted AMPK-α signaling and thereby upregulated autophagy accompanied with a light increase of P62 in osteosarcoma cells following TIIA treatment." (PMID 30258193, 2018). "Nevertheless, this study illustrates that TIIA effectively inhibits osteosarcoma growth by increased expression of HGK, which further upregulates the downstream target of SESN2." (PMID 30258193, 2018). "To investigate whether SESN2 and p-AMPK proteins were expressed in human osteosarcoma, we examined bone sections of patients with osteosarcoma and normal bone tissue by immunohistochemistry." (PMID 30258193, 2018). "TIIA treatment effectively inhibited soft agar colony formation of mock and BECN1 knockdown osteosarcoma cells, but not of SESN2 shRNA cells." (PMID 30258193, 2018). "The authors have speculated that increased level of SESN2 inhibits the endoplasmic stress signalling pathway PERK–eIF2α–CHOP following the treatment with cisplatin, doxorubicin and methotrexate, thereby upregulating autophagy in osteosarcoma cells." (PMID 37284849, 2023). "In contrast, SESN2 and p-AMPK staining were weak to absent in osteosarcoma tissue." (PMID 30258193, 2018).
cardiomyopathy (6 papers, 2018 to 2023). A disease of the heart muscle or myocardium proper. "It is also astonishing to find that H3K27me3 is reported to be a transcriptional-active marker for SESN2 expression in the doxorubicin-induced cardiomyopathy." (PMID 35722096, 2022). "In summary, JMJD3 aggravated chronic DOX-stimulation induced cardiomyopathy via decreasing H3K27me3 enrichment in the promoter region of SESN2." (PMID 33117796, 2020). "Jumonji domain-containing protein D3 (JMJD3), a histone demethylase, inhibited the transcription of Sesn2 by reducing the methylations of H3K27me3 in the promoter region of Sesn2 in cardiomyopathy." (PMID 33425907, 2020). "However, JMJD3 overexpression aggravated DOX-induced cardiomyopathy, which were alleviated by SESN2 overexpression." (PMID 33117796, 2020). "However, JMJD3 overexpression aggravated DOX-induced cardiomyopathy, which were relieved by SESN2 overexpression." (PMID 33117796, 2020). "To explore the expression changes of JMJD3 and SESN2 in dilated cardiomyopathy (DCM), we used heart samples from 7 clinic patients with cardiomyopathy and 3 healthy controls." (PMID 33117796, 2020). "Sestrin2 (SESN2), a stress-inducible protein, protected against doxorubicin (DOX)-induced cardiomyopathy by regulating mitophagy and mitochondrial function." (PMID 33117796, 2020). "Here, the expression of JMJD3 was increased and that of SESN2 was decreased in both the heart samples from patients with dilated cardiomyopathy and chronic DOX-stimulation induced cardiomyopathy." (PMID 33117796, 2020). "Genes associated with ER stress (e.g., ATF4, NUPR1, DDIT3, TRIB3, CHAC1, SESN2, HERPUD1) were upregulated and genes related to cardiomyopathy and sarcomeric structure (e.g., MYH7, SYNPO2L, LDB3, ACTN2, MYLK3) were downregulated by afatinib, sorafenib, or high-dose ponatinib." (PMID 37069550, 2023).
coronary artery disease (6 papers, 2020 to 2025). "Elevated plasma Sesn1, Sesn2, and Sesn3 levels were observed in patients with coronary artery disease (CAD)." (PMID 32626541, 2020). "Similarly, serum SESN2 levels in diabetic patients with coronary heart diseases were significantly lower compared with the diabetic group without complications." (PMID 39769227, 2024). "It has been shown that the risk of coronary artery disease and atherosclerosis increases if sestrin 2 levels are not sufficiently elevated." (PMID 38813505, 2023). "In a previous study, circulating Sesn1, Sesn2, and Sesn3 were reported to be increased in patients with coronary artery diseases, while the amplitude of the increase in Sesn levels was closely related to the degree of stenosis and oxidative stress in CAD patients." (PMID 32626541, 2020). "Previous studies have demonstrated significantly elevated serum SESN2 levels in patients with coronary artery disease (CAD) compared to those without, suggesting a protective role in these patients." (PMID 39636755, 2025).